TNF (tumor necrosis factor)
Diseases named in the same sentence as TNF in open-access papers (continued):
Sharing a sentence is not in itself a finding about the gene and the disease.
asthma (continued). "Proinflammatory cytokines such as TNF-α and IL-1β are potent multifunctional cytokines in the pathogenesis of many inflammatory diseases, including asthma and rhinitis." (PMID 23253436, 2012). "For other asthma-relevant genes such as TNF, IL-4, IL-10, CCL12 (MCP-5), CCL5 (RANTES), and CCR3, there were no significant IL-13-inducible or statin effects on gene expression." (PMID 22583375, 2012). "This is in agreement with previous studies in which fluticasone or salmeterol inhibited release of other asthma-relevant chemokines induced by TNF-α." (PMID 23034049, 2012). "The rate of apoptosis of bronchial epithelial cells is significantly higher in asthma patients than that in healthy people, and TNF-α is suggested to play a crucial role in this process." (PMID 22675381, 2012). "Interleukin-1β, CXCL10 (IP-10), and TNF are all Th1 polarized cytokines that play a role in the pathogenesis of asthma." (PMID 22583375, 2012). "In many studies, anti-TNF-α therapy has been regarded as an attractive strategy for the management of asthma." (PMID 23094102, 2012). "Increased expression of TNF-α was reported in severe and refractory asthma and TNF-α can inhibit CTGF expression." (PMID 23029004, 2012). "Following the alveolar macrophage depletion, physiological aggravation of the lung tissue in the GCE-asthma model mice was improved, and TNF-α-producing cells were reduced in the area." (PMID 23094102, 2012). "More importantly, we found that TNFα/anti-CD3/CD28-induced IL-8 production was dexamethasone-insensitive particularly in severe asthma." (PMID 22911818, 2012). "Increased levels of sputum eosinophils and sputum IL-5, increased peripheral blood mononuclear cell-derived TNF-α, IL-12, and decreased IFN-γ levels were associated with on-going asthma symptoms and airway hyperresponsiveness." (PMID 23043798, 2012). "It is unclear what the major cellular source of this TNFα is, however there are a subset of asthma patients with refractory asthma that have significantly increased levels of neutrophils." (PMID 22954301, 2012). "Interleukin (IL)-13, IL-4, interleukin 4 receptor (IL-4Ra), signal transducer and activator of transcription 6 (STAT6) and tumor necrosis factor-alpha (TNFα) genes are key inflammatory genes in the development of allergic diseases such as asthma." (PMID 22355322, 2012). "Depletion of alveolar macrophages reduced AHR and intracellular TNF-α level in pulmonary cell populations in the GCE-induced asthma model." (PMID 23094102, 2012). "Th2 lymphocytes are the key orchestrators of this inflammation, initiating and propagating inflammation through the release of their cytokines, IL-4, IL-5, and TNF-α in turn recruiting and activating eosinophils, the effector cells in asthma." (PMID 20953388, 2011). "For example, genetic polymorphisms within a tumor necrosis factor gene cluster on chromosome 6p (including the genes for TNF-α and lymphotoxin α) have been shown to influence asthma and asthma-related phenotypes." (PMID 22151743, 2011). "We have also recently reported that alternate day calorie restriction in overweight adults with asthma results in marked decline in circulating TNF-α levels with improvement in pulmonary functions and measures of quality of life." (PMID 21385360, 2011). "While the list of cytokines potentially involved in asthma is long, both TNFα and IL-13 have been the focus of considerable investigation." (PMID 21858195, 2011). "The most prevalent gene symbol in the retrieved abstracts for genetic association with asthma was IL4 (91 citations) followed by IL13 (75 citations) and TNF (73 citations)." (PMID 21103062, 2010). "Percentage proportions of CD4+ T cell staining positively for IL-2, IL-4, IL-10, IL-13, IFN-γ, and TNF-α in unstimulated whole blood were similar in children with asthma compared to healthy controls." (PMID 21197090, 2010).
asthma (continued). "Regulatory differences between parental and pediatric asthma were reflected by six of the eleven mediators analyzed (eotaxin, IL-4, IL-5, IL-10, IL-12, TNFα)." (PMID 21179211, 2010). "Disease related to inflammatory factor TNF-alpha includes a variety of category such as tuberculosis, Alzheimer's disease, and asthma." (PMID 20920206, 2010). "A similar proportion of patients as that observed in the anti-TNF cohort had a comorbid condition, although angina, asthma, COPD, and/or previous neoplasm were more common in the nonbiologic DMARD group." (PMID 20662063, 2010). "While others have demonstrated a decrease in serum concentrations of ECP, IL5, IL8, and TNF-α with montelukast therapy in asthma, allergic rhinitis, and cystic fibrosis, we were unable to show any decrease of these in children with dyspepsia." (PMID 19432972, 2009). "Variants in the proinflammatory cytokine gene tumor necrosis factor α [TNFA, GeneID 7124] have been linked to decrease in pulmonary function and asthma and wheezing in relation to O3 and sulfur dioxide exposure." (PMID 20049212, 2009). "The evoked inflammatory responses in our study also did not directly predict changes in the magnitude of activity within sACC, a reported observation for TNF-α responses to inflammatory challenge in subjects with asthma." (PMID 19423079, 2009). "In bronchial epithelial cells in vitro, Tn can be up-regulated by cytokines like transforming growth factor-β (TGF-β) and tumor necrosis factor-α (TNF-α), which are also operative in asthma." (PMID 18503712, 2008). "TNF-α increases bronchial tissue responsiveness, suggesting a role of inflammatory cytokines in asthma and COPD." (PMID 21157520, 2008). "Anti-TNFα drugs, including etanercept, have emerged as a possible treatment option for refractory asthma: reduction of symptoms, improvement in lung function, and reduction of bronchial hyperresponsiveness as a result of anti-TNFα intervention." (PMID 18234086, 2008). "Polymorphisms in the proinflammatory cytokine genes tumor necrosis factor-α (TNF) and lymphotoxin-α (LTA, also called TNF-β) have been associated with asthma and atopy in some studies." (PMID 17450233, 2007). "We used the case–parent triad design to investigate the association of TNF and LTA polymorphisms and haplotypes with childhood asthma and atopy in asthmatic children from Mexico City, an area with the highest ozone exposure in North America." (PMID 17450233, 2007). "The TNF-857 and LTA-753 SNPs in the promoter regions have also been associated with asthma and atopy." (PMID 17450233, 2007). "Specifically, a significant reduction in TNF-α levels was observed, particularly in patients with asthma, which supports the hypothesis that statins may modulate systemic inflammation in chronic respiratory diseases." (PMID 41555409, 2026). "Patients with RA treated with TNF inhibitors (TNFis) may experience type 2 inflammatory conditions such as asthma, atopic dermatitis or urticaria." (PMID 41536915, 2026). "TNF acts as a key receptor that promotes the expression and release of inflammatory mediators such as IL-6, contributing to excessive mucus secretion and airway inflammation characteristic of asthma." (PMID 41599256, 2026). "TNF‐α levels were higher in the NS of patients with AR than in those with asthma and controls." (PMID 41179970, 2025). "Asthma is one of the chronic respiratory inflammatory diseases, and in almost asthma patients, the levels of inflammation-related cytokines, such as IL-6 and TNF-α, are elevated." (PMID 40323927, 2025). "TNF-α is crucial in the pathogenesis of asthma and may serve as a candidate gene for the condition, with its overproduction contributing to acute and chronic inflammation, including asthma." (PMID 40443529, 2025).
asthma (continued). "In individuals with severe or treatment-resistant asthma, high levels of TNF-α have been detected in the airways, bronchoalveolar lavage fluid, and sputum, which correlates with heightened airway responsiveness, diminished lung function, and ongoing inflammation." (PMID 40564060, 2025). "First, PDGF‐BB was employed to activate ASMCs; however, other growth factors (e.g., TGF‐β, EGF, and FGF) and inflammatory cytokines (for example, IL‐4, IL‐13, and TNF‐α) may also contribute to ASMC dysfunction in diseases such as asthma." (PMID 40338178, 2025). "In addition to the difference observed in TNF‐α between severe and non‐severe asthma, median IL‐5 concentrations were also higher in the severe group (1.7 vs. 0.8 pg/mL; p = 0.010)." (PMID 41159221, 2025). "Alternatively, proinflammatory cytokines, particularly IL-1β and TNF-α, may amplify the inflammatory response in asthma and COPD and corelate to disease severity." (PMID 40136649, 2025). "In a HDM-induced asthma model, IMs are the primary source of IL-10, and they significantly alleviate neutrophil-dominated airway inflammation by inhibiting the expression of Th2/Th17-related inflammatory cytokines such as IL-13, IL-17, GM-CSF, and TNF-α." (PMID 40636260, 2025). "Adipose tissue is metabolically active and produces pro-inflammatory cytokines, including tumor necrosis factor-alpha (TNF-α), IL-6, and leptin, which may contribute to both systemic and airway inflammation in obese individuals with asthma." (PMID 40649123, 2025). "In asthma sufferers’ provoked sputum, TNF levels are noticeably elevated." (PMID 40136649, 2025). "TNF, a versatile pro-inflammatory cytokine, influences cellular proliferation, differentiation, and apoptosis, playing a significant role in the pathogenesis of asthma." (PMID 40420184, 2025). "Among the two, TNF-α is a potential target for asthma treatment, especially severe asthma." (PMID 40564060, 2025). "IL-1β and TNF-α induce IL-6, which plays a role in inflammation, autoimmunity, cancer, and asthma." (PMID 41155381, 2025). "In contrast, only 12% of ILC2s were positive for TNF-α in the Alt-alone model of asthma." (PMID 40526428, 2025). "Moreover, signals like TNF-α can enhance Th2 immune responses in asthma pathogenesis and RSV-induced disease." (PMID 40143308, 2025). "In addition to histopathological findings, TNF-α, which is immunohistochemically stained, is a pleiotropic cytokine that plays a role in various lung pathologies including fibrosis, emphysema, asthma, and smoking-related connective tissue damage." (PMID 39918746, 2025). "Increased levels of TNF-α have also been detected in the airways of patients with asthma, indicating this pro-inflammatory cytokine plays an important role in the pathogenesis of asthma." (PMID 40565216, 2025). "Key pathways affected by DEGs included cytochrome NOTCH signaling pathway, IL-17 signaling pathway, Herpes simplex virus 1 infection, Systemic lupus erythematosus, Asthma, Measles, Lysosome, TNF signaling pathway, T cell receptor signaling pathway, NOD-like receptor signaling pathway." (PMID 41227773, 2025). "Cytokine levels of TNF‐α (p = 0.043) and IL‐5 (p = 0.010) differed by asthma severity." (PMID 41159221, 2025). "NF-kappaB plays a crucial role in oxidative stress, as excessive activation perpetuates the production of inflammatory mediators in severe asthma and may exacerbate COPD, given its association with TNF-α, IL-8, and other inflammatory cells." (PMID 38774212, 2024). "Increased plasma levels of TNF-α in asthma have been reported previously." (PMID 39902293, 2024). "Because asthma manifests in different forms and phenotypes, the effect of TNF-α might differ among these variations." (PMID 39407835, 2024).
asthma (continued). "In mice with ova-induced bronchial asthma, the administration of EGCG via tail vein injection demonstrates a notable amelioration of asthma symptoms, along with a reduction in lung infiltration of inflammatory cells and levels of inflammatory factors IL-2, IL-6, and TNF-α." (PMID 39411430, 2024). "Elevated levels of TNF-α have been observed in patients with severe steroid-resistant asthma." (PMID 39664985, 2024). "This has however not been replicated in other studies likely due to differences in the study populations and suggesting that only patients with T2 high asthma and a hyperactive TNF axis may benefit from TNF-targeted therapy." (PMID 38710930, 2024). "Nonetheless, blocking TNF-α has served as a successful therapeutic target for asthma patients on corticosteroid treatment, while LTA facilitates the attachment of lymphotoxin β to the cell surface by forming heterotrimers with it when released into extracellular space." (PMID 39766875, 2024). "Biologic therapies targeting key inflammatory pathways involved in viral-induced exacerbations, such as interleukin (IL)-4, IL-5, and IL-13 in asthma, and tumor necrosis factor-alpha (TNF-α) and IL-1 in COPD, show potential for modulating airway inflammation and reducing respiratory symptoms." (PMID 39458339, 2024). "The children with asthma had an inflammatory profile that was characterized by increased levels of several pro-inflammatory cytokines, including IL-2, IL-5, IL-13, IL-17A, IL-22, IL-33, TNF-α, and reduced level of anti-inflammatory cytokine, IL-10." (PMID 39902293, 2024). "The function of TNF-α in asthma is multifaceted and interferes with several processes." (PMID 39407835, 2024). "Children with asthma had higher levels of IL-2 (p = 0.005), IL-5 (p < 0.001), IL-13 (p = 0.021), IL-17A (p < 0.001), IL-22 (p < 0.001), IL-33 (p < 0.001), TNF-α (p < 0.001), and lower levels of IL-10 (p = 0.046) and leptin (p < 0.001) compared to those without asthma." (PMID 39902293, 2024). "Thus, the disruption of IL-17 and TNF pathways not only drives chronic inflammation but also promotes the structural changes that underpin airway remodeling in asthma." (PMID 39850030, 2024). "Likewise, in children with exacerbated and controlled asthma, miR-181a expression negatively correlated with serum levels of TNF-α, IL-1β, and IL-6." (PMID 38337625, 2024). "TNFα is a potent stimulator of inflammatory responses in many pulmonary diseases such as asthma, chronic obstructive pulmonary disease (COPD), and acute lung injury/acute respiratory distress syndrome (ALI/ARDS) but also HAPE and high-altitude pulmonary hypertension." (PMID 39057617, 2024). "Although targeting TNFα has been found to be very effective in the treatment of some inflammatory conditions such as rheumatoid arthritis and inflammatory bowel disease, this mechanism has been found to be less useful than expected in severe asthma." (PMID 39194521, 2024). "Also, the same study reported that the levels of miR-21-5p in exosomes correlated positively with IgE levels and correlated negatively with plasma levels of TNF-α and IL-6 in patients with moderate–severe asthma." (PMID 38337625, 2024). "Perhaps with better characterization of unique asthma endotypes, a subset of patients with severe asthma that respond safely to TNFα blockade may be established." (PMID 39194521, 2024). "Notably, neutrophils intensify airway inflammation through the secretion of inflammatory mediators, such as IL-8 and TNF-α, with their effects markedly evident in cases of severe or refractory asthma." (PMID 38988356, 2024). "For example, tumor necrosis factor-α (TNF-α) responses by both stimulated CBMCs at birth and by peripheral blood mononuclear cells (PBMCs) at 3 months of age predicted higher rates of childhood asthma." (PMID 39683596, 2024).
asthma (continued). "Reductions to variable extents were observed for TNF-alpha mRNA levels (~20–90%) and lung inflammation scores (~0–60%) depending on the disease process and the treatment, with efficacy against asthma models being less evident than for LPS induced inflammation models." (PMID 37298407, 2023). "IL-6 and TNF-α are involved in the inflammatory reaction of asthma." (PMID 37492220, 2023). "Although anti-TNF-α has been shown to improve asthma control in animal models, patients with severe asthma have not benefited from this therapy because there is limited evidence of improved lung function and reduced asthma exacerbation." (PMID 37377958, 2023). "TNF-α is also known to induce histamine release from mast cells and to be involved in mast cell–smooth muscle interaction, contributing to airway hyperresponsiveness in asthma." (PMID 37998734, 2023). "Although anti-TNFα therapy has produced varied results in clinical trials, it has shown beneficial effects in subpopulations of asthma patients that warrant further understanding of the functional role of TNFα in asthma." (PMID 36760534, 2023). "Tumor necrosis factor alpha (TNFα) is an endogenous mediator and a pro-inflammatory cytokine that exerts indirect implications on amplified migration of ASMCs and induces the recruitment of neutrophils and eosinophils in asthma and COPD." (PMID 37809717, 2023). "presented three patients on dual biologics for rheumatic disease (two RA and other with Crohn ́s-associated arthritis) and concomitant asthma, combining mepolizumab or omalizumab with anti-TNF and no SAEs were reported." (PMID 37936691, 2023). "Increased levels of inflammatory markers have been demonstrated in patients with COPD and asthma, such as interleukin (IL)-6, tumor necrosis factor-alpha (TNF-α), IL-1β, C-reactive protein (CRP), as well as adipocytokines such as visfatin, apelin, adipolin, and FABP4." (PMID 37003999, 2023). "In our model, we also observed the production of epithelial-derived innate cytokines, that in addition to Th2 cytokines, make a great contribution to the inflammatory response in asthma, such as IL-1β, IL-6, and TNF-α, the latter being considered a marker of neutrophilic asthma." (PMID 36980265, 2023). "The combination of high levels of TNF-α with epithelial cell injury may lead to airway remodeling: a common feature of asthma." (PMID 37730940, 2023). "Additionally, IL-5 and IL-13 induce the production of other molecules, including eosinophil cationic protein, major basic protein, tumor necrosis factor, and eicosanoid pathway metabolites, all contributing to bronchial hyperreactivity." (PMID 37834850, 2023). "Our findings have revealed that obese asthma patients, despite the basic anti-inflammatory therapy, had elevated levels of inflammatory markers in blood plasma such as leptin, tumor necrosis factor-α (TNF-α), interleukin-2 (IL-2), IL-4, and IL-17a, leukotriene B4 (LTB4), and thromboxane B2 (TXB2)." (PMID 37367676, 2023). "Increased circulating adipokines, as well as elevated levels of IL-1β and TNF-α are associated with asthma in obese individuals, but not with allergic asthma." (PMID 36803977, 2023). "Many studies support the hypothesis that TNF-α plays an important pathobiological role in lung diseases, including severe refractory asthma and COPD." (PMID 37400851, 2023). "Inhibition of the pro-inflammatory cytokine TNF-α has been proven to be very efficacious in multiple chronic diseases, including rheumatoid arthritis and inflammatory bowel diseases, and has also been tested in asthma." (PMID 37199256, 2023). "In our study, we found ILC3s produced neutrophil chemoattractants including CXCL8, CXCL1, TNF-α and GM-CSF after IL-1β stimulation, suggesting ILC3s may mediate airway neutrophilia in asthma by release of neutrophil chemoattractants." (PMID 36949482, 2023). "Classically-activated macrophages are known producers of both TNF-α and IL-1β in asthma." (PMID 37445635, 2023).